ENSG00000278391
Gene: Miscellaneous RNA gene on chromosome Y (18,336,960 to 18,337,049, forward strand). Ensembl gene ENSG00000278391.
Gene Ontology:
Biological process: chromatin remodeling